CCR9 (C-C motif chemokine receptor 9)
Diseases named in the same sentence as CCR9 in open-access papers (continued):
Sharing a sentence is not in itself a finding about the gene and the disease.
typhoid fever (2 papers, 2017 to 2022). A bacterial infectious disorder contracted by consumption of food or drink contaminated with Salmonella typhi. "Here, we report that activated (CD38+) MAIT cells coexpressing CCR6 and CCR9 markers were significantly higher during typhoid fever in TD volunteers receiving the low-dose inoculum than in TD volunteers receiving the high-dose inoculum." (PMID 28428786, 2017). "Moreover, the magnitude of MAIT cells coexpressing CCR6 and CCR9 markers were significantly higher, during typhoid fever, in TD volunteers receiving the low-dose inoculum than in TD volunteers receiving the high-dose inoculum." (PMID 28428786, 2017). "Previously, we found that during typhoid fever, activated MAIT cells expressing CD57, CCR6, or CCR9 increased in all TF participants." (PMID 35772315, 2022). "Interestingly, MAIT cells from low-dose TD volunteers had higher levels of CD38 coexpressing CCR9, CCR6, and Ki67 during the development of typhoid fever than high-dose TD volunteers." (PMID 28428786, 2017). "Interestingly, we found that TD volunteers exposed to low doses of wild-type S. Typhi (103 CFU) had higher levels of CD8+ MAIT cells coexpressing CD38 and either CCR9, CCR6, or Ki67 during the development of typhoid fever than TD volunteers receiving a high dose of S. Typhi (104 CFU)." (PMID 28428786, 2017).
acute GVHD (1 paper, 2024). "The protective role of Treg cells in acute GVHD is well-known, and donor Treg cells with CCR9 overexpressing can further alleviate the severity of acute GVHD and prolong the survival of mice." (PMID 39840040, 2024). "Furthermore, CCR9 and its ligand CCL25 are highly expressed in the intestinal endothelial venules and Peyer’s patches and play a key role in the pathogenesis of acute GVHD." (PMID 39840040, 2024).
acute monocytic leukemia (1 paper, 2010). Acute monoblastic leukemia (AML-M5), is one of the most common subtypes of acute myeloid leukemia (AML) that is either comprised of more than 80% of monoblasts (AML-M5a) or 30-80% monoblasts with (pro)monocytic differentiation (AML-M5b). "Tumour necrosis factor alpha (TNFα) increased CCR9 expression on human acute monocytic leukemia cell line THP-1 monocytic cells." (PMID 20738854, 2010).
acute myeloid leukemia (1 paper, 2018). Acute myeloid leukemia (AML) is a group of neoplasms arising from precursor cells committed to the myeloid cell-line differentiation. "Intriguingly, a case report of a pediatric T-ALL expressing CCR9 (and CD103 or αEβ7 integrin) at diagnosis, that switched to acute myeloid leukemia at relapse with disease localization to the gut has been reported, suggesting a role for CCR9 in the gut tropism of these leukemic cells." (PMID 29666622, 2018).
breast tumor (1 paper, 2015). "Next, we assessed whether CCR9 expression in breast tumor cells affected T cell recognition directly or indirectly, for example, through CCR9 signaling-mediated increase in secretion of immune-suppressive factors." (PMID 25691366, 2015).
Candida infection (1 paper, 2012). "Of the chemoattractant mediators, several chemokines (Ccl25, Ccl27, Ccl28) and chemokine receptors (Ccr9, Ccr10, Cxcr5, Cxcr6, Cxcr7) associated with adaptive immunity were not induced after Candida infection." (PMID 22916017, 2012).
co-infection (1 paper, 2021). "In addition, the qPCR analysis showed the chemokines ccl4, ccr6, ccr9, and cd5 were significantly down-regulated during lice infection alone vs pre-infection, and comparable with that of co-infection." (PMID 35046944, 2021).
cutaneous melanoma (1 paper, 2019). A primary melanoma arising from atypical melanocytes in the skin. "Reference 97 to “Amersi, F.F.; Terando, A.M.; Goto, Y.; Scolyer, R.A.; Thompson, J.F.; Tran, A.N.; Faries, M.B.; Morton, D.L.; Hoon, D.S., Activation of CCR9/CCL25 in cutaneous melanoma mediates preferential metastasis to the small intestine." (PMID 31146450, 2019). "The correct reference is “Amersi, F.F.; Terando, A.M.; Goto, Y.; Scolyer, R.A.; Thompson, J.F.; Tran, A.N.; Faries, M.B.; Morton, D.L.; Hoon, D.S., Activation of CCR9/CCL25 in cutaneous melanoma mediates preferential metastasis to the small intestine." (PMID 31146450, 2019).
experimental autoimmune encephalomyelitis (1 paper, 2024). An autoimmune demyelinating disease of the central nervous system that is produced experimentally in animals by the injection of homogenized brain or spinal cord in Freund's adjuvant. "Toll-like receptor 4 (TLR4) plays a role in the pathogenesis of experimental autoimmune encephalomyelitis (EAE) by regulating CCL25/CCR9 expression in response to Th17 infiltration." (PMID 39199524, 2024).
graft versus host disease (1 paper, 2021). An immune system disorder that occurs after allogeneic hematopoietic stem cell transplant and is a reaction of donor immune cells against host tissues. "Furthermore, it was found that the CCR9+ subpopulation of pDCs produce less type I IFN than CCR9- pDCs and CCR9+ pDCs can induce more immunosuppressive Tregs in graft-versus-host disease models." (PMID 34497606, 2021).
ileus (1 paper, 2017). Decrease in peristalsis in the absence of a mechanical bowel obstruction. "The detection of CCR9-expressing T lymphocytes in the bloodstream of patients with post-operative ileus has been reported to potentially reflect dysmotility." (PMID 28327177, 2017).
infarct (1 paper, 2016). "Abrogation of CCR9 improved the post-MI survival rate and left ventricular (LV) dysfunction and decreased the infarct size." (PMID 27585634, 2016).
ischemic stroke (1 paper, 2025). A stroke disorder caused by obstruction of blood flow to the brain, due to thrombotic (local blood clot formation) or embolic (due to a blood clot or other material traveling from another site) event. "In ischemic stroke, we found that MPO, CALCRL, PPP5C, KTN1-AS1, CCR1, CTB-50L17.9, CCR9, ZNF362, ZIK1, ELP5, CKAP2, NUP88, and SEC16A show risk effects (OR > 1)." (PMID 40624693, 2025).
keloid (1 paper, 2020). An irregularly shaped, elevated mark on the skin caused by deposits of excessive amounts of collagen during wound healing. "We observed increased cellular infiltrates in keloid tissues, including T-cells, dendritic cells, mast cells, as well as greater IL-4rα+, CCR9+, and periostin+ immunostaining." (PMID 33329590, 2020). "Both CCR9, the homing receptor for the small intestine and lung, and its ligand CCL25, displayed increased expression in keloid tissues (FDR ≤ 0.1)." (PMID 33329590, 2020).
kidney (1 paper, 2024). "In contrast, kidney transplant patients under immunosuppression showed no expansion of gut-homing Beta7+CCR9+ Tregs 30 days after propionic acid intake." (PMID 39328339, 2024).
lupus (1 paper, 2021). "In addition, we found that the expression of CD27, Anxa9, CCR9, and IL17Rβ were decreased in M-MDSCs from pristane-induce lupus mice, and INK128 could increase the expression of these genes." (PMID 34282122, 2021).
lymphopenia (1 paper, 2020). Reduction in the number of lymphocytes. "We demonstrated that the observed lymphopenia postinfusion is due to a combined RMD effect, consisting of (i) apoptosis; (ii) downregulation of cell surface markers CD3, CD4, and CD8; (iii) upregulation of homing markers α4β7, CCR7, and CCR9; and (iv) migration from the periphery to the gut and LNs." (PMID 33362765, 2020).
metastatic melanoma (1 paper, 2011). A melanoma that has spread from its primary site to another anatomic site. "As such, we could detect expressions of CCR5, CCR9 and CXCR3 in all malignant metastatic melanoma cells, using a immunohistochemistry protocol described previously." (PMID 21179030, 2011).
metastatic tumor (1 paper, 2014). "Interestingly, higher expression of CCR9 in NSCLC correlated with tumor size (T); higher tumor size is often associated with metastatic tumor." (PMID 25296976, 2014).
mucinous adenocarcinoma (1 paper, 2010). An invasive adenocarcinoma composed of malignant glandular cells which contain intracytoplasmic mucin. "Our results show significantly (p < 0.001) higher expression of CCR9 by mucinous adenocarcinoma, papillary serous carcinoma, and endometriod ovarian carcinoma cases, than compared to non-neoplastic ovarian tissue." (PMID 20649989, 2010). "While CCR9 expression by mucinous adenocarcinoma was lower than endometriod and papillary serous carcinomas, these OvCa cases significantly (p < 0.001) expressed CCR9 compared to non-neoplastic ovarian tissue." (PMID 20649989, 2010). "In general, OvCa tissues significantly (p < 0.001) expressed CCR9 compared to non-neoplastic tissue, as did papillary serous and endometroid carcinomas compared to mucinous adenocarcinoma." (PMID 20649989, 2010). "Ovarian TMAs consisting of non-neoplastic, mucinous adenocarcinoma, papillary serous carcinoma, and endometriod carcinoma tissues were evaluated for CCR9 expression." (PMID 20649989, 2010). "Here we show for the first time that normal ovarian epithelial cells and non-neoplastic tissues express low levels of CCR9, while OvCa cell lines and mucinous adenocarcinoma, papillary serous carcinoma, and endometriod carcinoma tissues express high levels of CCR9." (PMID 20649989, 2010). "Interestingly, we found the highest expression of CCR9 in serous papillary and endometroid carcinomas in comparison to non-neoplastic and to a lesser degree in mucinous adenocarcinoma cases." (PMID 20649989, 2010).
pancreatitis (1 paper, 2024). Inflammation of the pancreas. "In parallel studies, we investigated the involvement of the interaction between CCR9 and CCL25 by assessment of pancreatitis following administration of anti-CCL25 Ab or control Ab." (PMID 39264798, 2024).
papillary serous carcinomas (1 paper, 2010). "The highest expression of CCR9 was observed in endometriod carcinoma followed by papillary serous carcinomas." (PMID 20649989, 2010).
parasitic infection (1 paper, 2019). "In addition, the upregulation of ccl25/ccr9 was found after parasitic infection of fish." (PMID 31277329, 2019).
SARS-CoV infection (1 paper, 2022). "The increased numbers of proinflammatory monocytes in both the Ccr9- and Cxcr6-deficient mice suggest a potential mechanism for increased disease severity, as previous studies have implicated the levels of proinflammatory monocytes cells in lethal SARS-CoV infection." (PMID 35862771, 2022).
secondary progressive multiple sclerosis (1 paper, 2019). A multiple sclerosis with a clinical course characterized by a progressive accumulation of neurological disability, independent of relapses, following an initial relapsing-remitting (RR) phase. "Moreover, CCR9+ memory T cells in CSF of patients with secondary progressive multiple sclerosis expressed high level of LAG3 and RORγt." (PMID 31354747, 2019).
Stroke (1 paper, 2025). Sudden impairment of blood flow to a part of the brain due to occlusion or rupture of an artery to the brain. "CCR9 plays a role in immune cell migration and inflammation; while primarily related to gut immunity, systemic inflammation involving CCR9 may impact vascular health and stroke susceptibility." (PMID 40624693, 2025).
type 2 diabetes (1 paper, 2024). "Furthermore, the study investigating the role of the CCL25/CCR9 axis in the pathogenesis of type 2 diabetes identified a key role of CCR9 in inducing glycose intolerance via inducing the infiltration of CD4+ T cells in the small intestine." (PMID 39411316, 2024).
Ventricular arrhythmia (1 paper, 2016). "The ratio of sustained ventricular arrhythmias was reduced in the CCR9−/− MI mice compared with the CCR9+/+ MI mice." (PMID 27585634, 2016).
vitamin A deficiency (1 paper, 2012). Deficiency of vitamin A due to malnutrition, malabsorption, or dietary lack. "Baseline CCR9 expression on CD4+ T cells in naïve, uninfected mice was reduced as a result of vitamin A deficiency in the MLN and intestinal mucosa but not in the spleen, confirming previous reports that homeostatic RA synthesis is a selective function of APCs in the GALT." (PMID 22927819, 2012).
tumor (87 papers, 2010 to 2025). "Several investigations have reported a strong association between CCL7, CCL13, CXCL5, and CCR9 and tumorigenesis as well as tumor development." (PMID 41465903, 2025). "Whereas the number of CCR9-expressing ɣδ T decreased in the blood, their frequency tended to increase in the tumor bed, despite a possible loss of expression in this environment." (PMID 36875124, 2023). "Immunohistochemistry staining and RT–qPCR analyses were performed to detect the correlation of CCR9 expression and tumor progression-associated markers in SACC." (PMID 36003306, 2022). "CCR9, which belongs to the chemokine receptor family, has been found to be expressed in tumors and to be closely associated with tumor proliferation, apoptosis, and metastasis." (PMID 34863167, 2021). "Previous studies have reported that CCL25/CCR9 is associated with tumor migration, invasion, and antiapoptosis in PC." (PMID 33195424, 2020). "In the past decade, chemokine ligand 25 (CCL25)/chemokine receptor 9 (CCR9) have been found in a wide variety of tumors and have been associated with tumor chemoresistance and metastasis." (PMID 26879872, 2016). "Taken together, these results suggest an important role for tumor-associated CCR9 as an immune-checkpoint node for application in cancer immunotherapy." (PMID 25691366, 2015). "We next wondered if these gene signatures observed in T cells upon tumor-specific CCR9 knockdown overlap with gene signatures generally associated with an activated T cell population." (PMID 25691366, 2015). "According to the classification described in the section of Methods, immunohistochemical analysis clearly showed that the CCR9 expression at the protein level was significantly and positively associated with the tumor size (P = 0.032)." (PMID 26168791, 2015). "92R inhibits human CCR9+ tumor growth in T and B-cell deficient Rag2−/− mice." (PMID 29434597, 2018). "However, this chemokine may cause infiltration of the tumor by cytotoxic TIL exhibiting CCR9 expression, which has an anticancer effect." (PMID 33076281, 2020). "Moreover, the expression of CCR9 and has been associated with tumor chemoresistance and metastasis." (PMID 32957689, 2020). "Our data demonstrate that CCR9 shapes the tumor microenvironment, affecting the recruitment of effector CD4+, CD8+ and Treg cells subsets." (PMID 40305493, 2025). "Among these receptors, it has been identified that the chemokine receptor CCR9 is expressed differentially in the tumor and non-tumor areas, showing a decreased percentage of CCR9+ CD8+ T cells in CRC compared to normal tissue." (PMID 40305493, 2025). "Studies have shown that oral administration of Akkermansia muciniphila can increase the recruitment of CCR9+CXCR3+CD4+ T lymphocytes to the tumor bed, thereby restoring the efficacy of PD-1 inhibitors in NSCLC patients." (PMID 40406244, 2025). "Clinically, elevated CCR9 expression correlates with advanced tumor grade, lymph node metastasis, and poor survival, independent of histologic subtype." (PMID 40607416, 2025). "As a representative species, Akkermansia muciniphila has been shown to restore the efficacy of PD-1 blockade in an interleukin-12-dependent manner by increasing the recruitment of CCR9+CXCR3+CD4+ T cells into the tumor microenvironment." (PMID 41304278, 2025). "Mechanistically, Akkermansia induced IL-12 production, which promoted the infiltration of CCR9+CXCR3+CD4+ T lymphocytes into the tumor microenvironment, thereby rescuing ICI responsiveness." (PMID 41030553, 2025). "To evaluate the effect of CCR9 on tumor growth, we isolated colon tissue from mice at the end of the experimental model (Day 60)." (PMID 40305493, 2025). "Recent studies have found that the intestinal flora Akkermansia muciniphila restores the efficacy of PD-1 blockade by increasing recruitment of CCR9+ CXCR3+ CD4+ T lymphocytes to mouse tumor beds in an IL-12-dependent manner." (PMID 38790057, 2024).
tumor (continued). "Data from previous studies have established that CCR9/CCL25 interaction promote tumor proliferation, invasion, anti-apoptosis, and migration in a variety of malignant tumors." (PMID 39416786, 2024). "Through the facilitation of the recruitment of CCR9+CXCR3+CD4+ T lymphocytes to the tumor tissue in mice, AKK bacteria can initiate an antigen-specific T cell response." (PMID 38617841, 2024). "Our results also revealed that tumor cells express CCR9, with CCR9 levels significantly upregulated following NAT10 knockdown." (PMID 39648231, 2024). "The immunological changes induced by A. muciniphila and E. hirae in mice included the promotion of IL-12 secretion by dendritic cells and the accumulation of CCR9+ CXCR3+ CD4+ T cells in the tumour microenvironment." (PMID 39634265, 2024). "Analysis of the Human Protein Atlas allowed to pinpoint CCR9 as a potential immunotherapeutic target for T-ALL, and analysis of GENT2 allowed to determine the specificity of CCR9 expression in normal and tumor tissue samples." (PMID 38132155, 2023). "Consistent with this, such a diet promotes the activation of ɣδ T IELs in the gut and we found that the frequency of CCR9+ tumor-infiltrating cells tends to increase, suggesting a possible intestinal origin of ɣδ TILs." (PMID 36875124, 2023). "Supplementation with A. muciniphila increased the recruitment of CCR9 + CXCR3 + CD4+ T lymphocytes into mouse tumor beds in an IL-12-dependent way." (PMID 37111034, 2023). "For the bone marrow, 17.7% of the cells represent endogenous mouse cells and 82.3% represent tumor cells, where 99.8% were CD45+CCR9+ and only the 0.02% of the tumor cells were CD45+ with a decreased expression of CCR9." (PMID 35967322, 2022). "The interaction of CCL25 and CCR9 promotes tumor growth and metastasis in SACC by activating the PI3K/AKT signaling pathway, offering a promising strategy for SACC treatment." (PMID 36003306, 2022). "CCR9 was highly expressed in SACC compared with adjacent salivary gland tissues, and its level was associated with tumor proliferation and metastases." (PMID 36003306, 2022). "Investigators have recently demonstrated that replenishing the gut microbiome with Akkermansia muciniphila in germ-free mice receiving FMTs from patients responding to immunotherapy promotes CCR9 + CXCR3 + CD4 + T-lymphocyte migration into tumor beds." (PMID 35073876, 2022). "Increasing evidence points to an important role for CCR9 in guiding mobilized, CCR9-expressing tumor cells to the gastrointestinal tract, notably the intestines, where its single ligand CCL25 is ubiquitously produced." (PMID 35158783, 2022). "From the tumor cells, the 99.4% were CD45+CCR9+ and only the 0.5% of the tumor cells were CD45+ with a decreased expression of CCR9." (PMID 35967322, 2022). "As a result, the promotion of CCR9+CD8+ T-cell infiltration enhanced the antitumor effect induced through the downregulation of CD47 expression and caused tumor growth arrest and the inhibition of metastatic dissemination." (PMID 35335881, 2022). "For instance, it has been shown that A. muciniphila promotes the accumulation of CCR9+ T cells, and such cells are subsequently found among tumor-infiltrating T cells." (PMID 34835287, 2021). "Akkermansia muciniphila and Faecalibacterium pausnitzii have demonstrated significant benefits in recruiting CCR9+CXCR3+CD4+ T lymphocytes to the tumor microenvironment through the mediation of IL-12." (PMID 33578709, 2021). "It is conceivable that the chemokine axis is reshuffled by cytotoxic agents in both ileal and tumor epithelia in an inversed manner, changing the homing equilibrium between gut to tumor beds, as previously shown for CCR9+ T cells." (PMID 33262469, 2021). "Our experiments indicated that CCR9 expression in the primary tumor site was higher in OS patients with lung metastasis than in those without lung metastasis." (PMID 34863167, 2021).